FOXP3 (forkhead box P3)
Diseases named in the same sentence as FOXP3 in open-access papers (continued):
Sharing a sentence is not in itself a finding about the gene and the disease.
colitis (continued). "Attenuation of the systemic inflammation in colitis and EAE models by daily oral administration of PG depends on suppression of T-helper 17 (Th17) lineage differentiation and an induction of Foxp3+ regulatory T (Treg) cells." (PMID 25032213, 2014). "For example, VIP treatment of mice with TNBS-induced colitis induces tolerance responses, dampening TLR2- and TLR4-induced inflammation and increasing expression of Foxp3 and TGFβ, as it does in a rat model of collagen-induced arthritis." (PMID 24550907, 2014). "FOXP3+ cells, CD4+CD25+FOXP3+ cells, and IL-10-secreting CD4+CD25+ T cells all play key roles in the regulation and suppression of DSS-induced colitis." (PMID 23864893, 2013). "However, the chemokine-blocking treatment did not affect the body weight loss in DSS colitis model, indicating that other factors such as increased production of pro-inflammatory cytokines and decreased cLP Foxp3 Treg cell fraction play an important role in the disease development." (PMID 23776480, 2013). "In models of colitis driven by IL-17A+ or IL-17A+IFN-γ+ T cells, suppression of disease by Foxp3+ Treg or Tr1 cells required direct IL-10 signaling into the effector T cells." (PMID 23405904, 2013). "In another mouse model of colitis, oral ingestion of Lactobacillus casei alleviated colitis and increased the suppressive function of CD4+Foxp3+ Tregs." (PMID 22970150, 2012). "The CD4+FoxP3+CD103+ subset expresses CTLA-4; suppresses T cell proliferation in vitro; and protects mice from colitis in the severe combined immunodeficient (SCID) transfer model in vivo." (PMID 21966415, 2011). "However, although CD4+CD25+FoxP3+regulatory T cells (Tregs) are known to suppress Th1-mediated colitis, it is not clear whether they control Th2 –associated pathologies of the large intestine which characterise several helminth infections." (PMID 21858239, 2011). "CD4cre mice have significantly fewer CD4+FoxP3+ Tregs in blood and IL10-expressing CD4+ T cells in the MLN on day 7 of DSS colitis in comparison to WT mice." (PMID 20537136, 2010). "Thus, in the presence of IL-23R-responsive WT T cells there is a reduction in the ability of Il23r−/− T cells to produce IL-10, which may explain the development of colitis in mice given a mixture of WT and Il23r−/− T cells, despite increases in the percentage of Foxp3+ Treg cells." (PMID 20732640, 2010). "These Foxp3+ cells appear to play a functional role in protection from IL-23-independent inflammation because transfer of Foxp3-deficient T cells to Il23a−/−Rag1−/− hosts induces severe colitis, indistinguishable from disease induced after T cell transfer into IL-23-sufficient Rag1−/− recipients." (PMID 18400195, 2008). "Since Treg levels are increased in DSS-induced colitis on day 8, but we wanted to focus on conventional T helper cells, we made use of the FoxP3-GFP reporter mice to analyze all non-Treg cells by gating on FoxP3-negative CD4+ T cells." (PMID 40422192, 2025). "The high proportion of FoxP3+CD25+ cells indicates a highly enriched population of functionally suppressive Tregs, supporting their suitability for therapeutic application in DSS-induced colitis." (PMID 40622253, 2025). "Furthermore, under colitis conditions, ERAP1+/− mice exhibited a 64% decrease in Foxp3 expression compared with WT mice." (PMID 40977735, 2025). "It significantly boosted FoxP3 expression, demethylated multiple CpG sites in the FoxP3 promoter, and activated AHR, which may have contributed to colitis protection." (PMID 39203033, 2024). "The enhanced regulatory function of Ctsw−/− pTreg cells was further evaluated in a T cell cotransfer colitis model.WT CD4+CD25−CD45RBhi cells were transferred into Rag2−/− mice, together with either WT or Ctsw−/− in vitro–differentiated Foxp3+ (GFP) pTreg cells at a ratio of 10:1." (PMID 37436991, 2023).
colitis (continued). "In addition, SCFAs promote the expression of Foxp3 by activating GPR43 on T cells and induce the polarisation of intestinal T cells to Tregs in mice with colitis to inhibit the inflammatory response." (PMID 37596634, 2023). "CD69+CD103− CD4+ TRM cells only accounted for 19.1% and 15.0% of Foxp3+ Treg cells in the colon of mice with or without DSS-induced colitis, respectively." (PMID 35844584, 2022). "We also show that lack of AIM2 also supports the stability FOXP3+ cells in vitro and their differentiation in vivo during a naïve T cell transfer model of colitis." (PMID 35216346, 2022). "Majority of the CD69+CD103+ CD4+ TRM cells were Foxp3+ Treg cells that more than 70% of Foxp3+ Treg cells were CD69+CD103+ CD4+ TRM cells both in mice with or without colitis." (PMID 35844584, 2022). "Interestingly, in the murine colitis model, we demonstrate that an increased frequency of STAT3 GOF Tregs that had downregulated Foxp3 expression became IL-17A–producing ex-Tregs." (PMID 36136607, 2022). "Indeed, an initial short treatment of experimental IBD with analogue 5 increased the number of MLN Foxp3 + CD4 + CD25 + Treg cells and the gene expression of colonic FoxP3, as well as inducing tolerance to colitis recurrence." (PMID 33767180, 2021). "We found that ET could alleviate colitis in the adoptive T cell transfer model of colitis if TGF-β and IL-10 were present but Foxp3+ Tregs were dispensable." (PMID 33717186, 2021). "Here, the augment of Helicobacter and H. ganmani may contribute to the induction of RORγt+ Foxp3+ Treg cells, both of which were responsible for the mechanism whereby FMT from GML-treated mice achieved a faster remission of DSS-induced colitis." (PMID 34634946, 2021). "Given the ability to alleviate colitis independent of the presence of Foxp3+ Tregs, Tregs that can secrete TGF-β and mediate oral tolerance were likely involved." (PMID 33717186, 2021). "The colonic Foxp3 mRNA was significantly decreased in the colitis group, which was not significantly affected by 20 and 80 mg/kg aucuboside." (PMID 34335262, 2021). "Subsequently, the rescue of adoptive transfer colitis was examined in absence of pTreg cells by transferring in naïve T cells from mice lacking functional FOXP3 (Foxp3ΔEGFP)." (PMID 34421921, 2021). "Therefore, L.p R3 strain inhibits the expression of IFN-γ and IL-17A, while promotes the expression of CD25, Foxp3 and IL-10 in murine DSS-induced colitis tissue." (PMID 34407839, 2021). "We concluded that the improved glucose tolerance and insulin sensitivity we observed in the SFD-fed Blimp-1fl/fl Foxp3-Cre+ mice was not due to colitis." (PMID 33351782, 2021). "Of note, the T cell response to the colitis process was totally blunted in the treated group, an effect evidenced across different T cell subpopulations, such as cytotoxic CD8+ T cells, Th1 (CD4+IFNg+), Th2 (CD4+IL4+), Th17 (CD4+IL17+), and Tregs (CD4+FoxP3+)." (PMID 34072532, 2021). "After 7-days’ administration of SSP and 5-ASA, the numbers of CD4+CXCR5+IL-10+ (Tfh10) and CD4+CXCR5+Foxp3+ (Tfr) (E5) were dramatically increased when compared with those in colitis mice without treatment." (PMID 32581849, 2020). "Indeed, not only are ICOS+ Tregs capable of maintaining T cell tolerance, various FOXP3– regulatory T cells, such as Tr1 cells and Treg-of-B cells, which also express ICOS, can protect mice from experimental colitis." (PMID 32983168, 2020). "In CD4+ Tconv, ectopic expression of FOXP3 using retroviral vectors or by HDR of a strong promoter upstream of the FOXP3 coding sequences allowed generation of Treg that suppressed CD4+ Tconv not only in vitro but also inhibited GvHD, colitis or dermatitis in animal models." (PMID 33717052, 2020). "In another study involving colitis, it was shown that activation of CB2 by JTE907 promotes the differentiation of Th0 cells into the Treg cell phenotype, which was characterized by the expression of FoxP3, TGF-β, and IL-10." (PMID 32612530, 2020).
colitis (continued). "Western blot analysis of colon tissues revealed that cyclooxygenase-2, tumor necrosis factor alpha (TNF-α), and phosphorylated signal transducer and activator of transcription-3 (p-STAT3) were significantly decreased in the colitis + 5-ASA group, whereas forkhead box P3 (FOXP3) was increased." (PMID 33092149, 2020). "The results showed that Foxp3 mRNA and protein expression in colonic tissue samples was dramatically decreased in the TNBS-induced colitis model group but increased in the PF (5, 10 and 20 mg/kg), PF-treated DC, SASP and prednisone groups compared with the TNBS-induced colitis model group." (PMID 32472435, 2020). "Similarly, IL-33 signaling on TREG cells was shown to play an important role in enhancing the stability of Foxp3 in TREG cells and is notably necessary for these cells to prevent T cell-mediated colitis." (PMID 30949175, 2019). "Foxp3‐K262R transductants, on the other hand, failed to prevent severe colitis and mice receiving these “engineered Tregs” resembled no‐Treg controls in terms of weight loss." (PMID 30886050, 2019). "Conditional knock out mice lacking Maf in all T cells developed spontaneous late-onset colitis, correlating with a decrease of FOXP3+RORγt+ T cells proportion, dampened IL-10 production in the colon and an increase of inflammatory TH17 cells." (PMID 30992496, 2019). "To explore whether repeated administration of DSS also has systemic effects, we examined Th1, Th2, Th17 and CD4+Foxp3+ Tregs in blood and MLNs in animals with acute or chronic DSS colitis." (PMID 31296924, 2019). "In MLNs cells, Foxp3+ Treg peaked in preventive group (6.16 ± 0.48) followed by S. obv group (5.17 ± 0.27) and therapeutic group (4.86 ± 0.28) but barely noticed in control group (3.55 ± 0.46) and DSS colitis group (2.26 ± 0.26)." (PMID 31836772, 2019). "We now show that during the late phases of induced colitis, phosphorylation of STAT3 is present on nearly 20% of all cLP CD3+FoxP3−RORγt+ and CD3+FoxP3−RORγt− cells, while it is barely expressed in CD3+FoxP3+ RORγt− regulatory T cells." (PMID 30619314, 2018). "Furthermore, alpinetin significantly promoted expression of miR-302 but not others, and restrained expression of DNMT-1 and methylation level of Foxp3 promoter region in CD4+ T cells and colons of colitis mice." (PMID 30166541, 2018). "We previously reported that CD8+CD103+ Treg induced ex vivo with TGF-β1 and IL-2 (CD8+CD103+ iTreg), regardless of Foxp3 expression, displayed potent immunosuppressive effect on Th cell response and had therapeutic effect on Th cell-mediated colitis." (PMID 29441062, 2018). "Meanwhile, Bifico could increase the colonic Foxp3 protein level, but decrease the colonic CD4 protein level in colitis mice." (PMID 29849501, 2018). "We previously reported that CD8+CD103+ iTreg induced ex vivo with TGF-β and IL-2 potently suppressed Th cell response and Th1/Th17-mediated colitis, regardless of Foxp3 expression." (PMID 29441062, 2018). "In addition, aloperine regulated T-cell proportions and promoted Foxp3 expression in the spleens and mesenteric lymph nodes of DSS-induced colitis mice and in the spleens of the Foxp3GFP mice." (PMID 29056830, 2017). "Moreover, upon TNBS induction, Ash1l-silenced mice had fewer Foxp3+ Treg cells in the spleen and mLN, indicating that Ash1l could promote Treg cell differentiation in vivo under pathological conditions, which is critical for the prevention of overall inflammatory responses in colitis." (PMID 28598443, 2017). "Previous studies have determined that S. japonicum-secreted Sj-Cys could stimulate CD4+CD25+Foxp3+ Treg cells, alleviate the Th1 dominated immunopathogenesis and actively restrain the colonic inflammation in TNBS-induced experimental colitis in mice." (PMID 28482922, 2017).
colitis (continued). "Surprisingly, mice overexpressing Bcl-3 specifically in Treg cells (Bcl-3FoxP3OE mice) did not develop any signs of colitis probably due to the very high percentage of GFP− Foxp3+ Treg cells, which was less pronounced using CD4-Cre." (PMID 28452361, 2017). "Furthermore in the T cell transfer colitis model, IFNAR signaling of host hematopoietic cells was important to limit effector cell expansion and to promote the stabilization of Foxp3+ Tregs." (PMID 28352268, 2017). "Interestingly, antibiotics, which prevented the development of colitis, suppressed the expansion of total FoxP3+ and CD25-FoxP3+ Tregs, thus indicating that this CD25-negative Treg population expands as a consequence of inflammation and/or dysbiosis." (PMID 27050757, 2016). "Antigens derived from multiple microbes in these genera, including Parabacteroides distasonis, have been shown to induce the differentiation of colonic FoxP3+ Treg cells, and administration of P. distasonis-derived antigens ameliorates the severity of DSS-induced colitis." (PMID 25675094, 2015). "In contrast, increased CD4+FoxP3+ cell population as well as secretion of TGF-β, prostaglandin E2 (PGE2) and lipoxin A4 (LXA4) was observed in TNBS-colitis mice treated with CTX compared with untreated TNBS-colitis mice." (PMID 25853847, 2015). "IL-10 produced by Treg cells is critical for their function as FoxP3+ T cells lacking IL-10 are unable to suppress the development of gastritis and colitis." (PMID 25807464, 2015). "Similarly, the extracellular polysaccharide A of Bacteroides fragilis, has also been shown to expand the number of mucosal Foxp3+ T cells and confers a TLR2-dependent protection in mouse colitis models." (PMID 25910186, 2015). "Consistent with normal levels of Foxp3 in the recovered Tregs, Hif1a-knockout re-established the ability of Dtx1−/− tTregs to repress CD4+CD25− T cell-induced colitis in Rag1−/− mice as determined by colitis score readout, body weight loss and intestinal morphology." (PMID 25695215, 2015). "The results suggest that ERCs may have regulatory functions on the cell populations of splenic CD3+CD25+ active T cells, CD3+CD8+ T cells, CD4+CD25+ Foxp3+ Tregs and CD11c+MHC-II+ DCs in the colitis mice." (PMID 25475342, 2014). "A recent study demonstrated that in vitro-derived iTreg cells cotransferred with naïve T cells into Rag−/− hosts were not effective in preventing colitis and many of the iTreg cells had decreased Foxp3, CTLA-4, and CD25 expression." (PMID 23801990, 2013). "Mice with selective knockout of IL-10 in Foxp3-expressing cells (IL-10fl/fl × FoxP3-cre) do not develop spontaneous systemic autoimmunity but do develop spontaneous colitis in a similar manner to germline IL-10-knockout animals." (PMID 23755052, 2013). "In this acute colitis model in mice with an intact immune system we did not detect histological changes in the lung and liver due to the absence of Foxp3+ Treg (data not shown)." (PMID 22849659, 2012). "Thus, the hyperplastic mucosa in established colitis was heavily infiltrated by a ten-fold increase in CD4+ T cells, and the proportion of FoxP3+ cells rose by two- to three-fold." (PMID 21966415, 2011). "During acute DSS-colitis, mice receiving vehicle showed a significant drop in total percentage of CD4+CD25+FoxP3+ splenocytes, while mice receiving cis-UCA maintained pre-DSS levels of CD4+CD25+FoxP3+ cells and were significantly higher than PBS control levels." (PMID 21060867, 2010). "Together, these data argue against an abnormal development of Th17 cells in the absence of functional Foxp3 in this system and point to a direct role of Foxp3 in inhibiting colitis in the absence of IL-23." (PMID 18400195, 2008).
colitis (continued). "Notably, APS significantly down-regulated the percentages of Th17 (CD4+CCR6+), cmTh17 (CD4+CCR7+CCR6+) and emTh17 (CD4+CCR7−CCR6+) cells and significantly up-regulated the percentages of cmTreg (CD4+CCR7+Foxp3+) and emTreg (CD4+CCR7−Foxp3+) cells in the mesenteric lymph nodes of the colitis mice." (PMID 38202824, 2024). "In line with our results in Il10−/−Mdr2−/− mice, colitis severity and CD4+ T-cell infiltration in the inflamed colon of Il10−/− mice was attenuated under the DDC diet, and frequencies of colonic Foxp3+ Treg cells were increased compared with the regular chow diet." (PMID 38839272, 2024). "Importantly, APS reversed the expression changes in the TIGIT molecule on mTh17/mTreg cells in the colitis mice with fewer CD4+CCR6+TIGIT+, CD4+CCR7−CCR6+TIGIT+ and CD4+CCR7−CCR6+TIGIT+ cells and more CD4+Foxp3+TIGIT+, CD4+CCR7−Foxp3+TIGIT+ and CD4+CCR7−Foxp3+TIGIT+ cells." (PMID 38202824, 2024). "Critically, the colitis mice also exhibited an abnormal imbalance of mTh17/mTreg cells with higher frequencies of CD4+CCR7+CCR6+ cmTh17 and CD4+CCR7−CCR6+ emTh17 cells and lower frequencies of CD4+CCR7+Foxp3+ cmTreg and CD4+CCR7−Foxp3+ emTreg cells in the MLNs." (PMID 38202824, 2024). "Furthermore, Il23a−/−Rag2−/− mice that received Foxp3−/− naïve T cells, which are unable to differentiate into pTregs, developed severe colitis, whereas those that received WT naïve T cells did not." (PMID 39379604, 2024). "Together, these data suggest that LA could increase macrophage infiltration and induce proinflammatory cytokines expression in macrophage, which inhibited Foxp3 expression and subsequent Treg cell differentiation and resulted in increased susceptivity to DSS‐induced colitis." (PMID 38477534, 2024). "Nevertheless, though the CD3+Foxp3+ MLN cells were decreased, the concomitant reduction in IL-10 producing lymphocytes at these draining lymph nodes, together with an outstanding splenic TNF production, reiterates the pro-inflammatory potential of MLT in experimental colitis." (PMID 36838425, 2023). "Although colitis in this model was accredited to the production of the Th1 cytokine IFN-γ, enhanced emergence of IL-17A+IFN-γ population of T cells and suppression of populations of Foxp3+ and IL-10-producing regulatory T cells was attributed to IL-23R signalling in T cells." (PMID 36012618, 2022). "However, as with Foxp3, following pretreatment with this compound, there was no improvement in the symptoms of colitis." (PMID 36077306, 2022). "However, neither percentages nor cell numbers of Foxp3+ Treg cells were changed in DSS-induced colitis." (PMID 35844584, 2022). "In this study, CD4+CCR7+/− cells in mice with DSS-induced colitis were overactivated, and their subsets CD4+CCR7+IL-17A+ and CD4+CCR7−IL-17A+ increased significantly, while CD4+CCR7+IL-10+, CD4+CCR7−IL-10+, CD4+CCR7+Foxp3+, and CD4+CCR7−Foxp3+ decreased significantly." (PMID 35832382, 2022). "Like our previous findings, we found that ET could alleviate colitis independent of the presence of Foxp3+ Tregs." (PMID 33717186, 2021). "To further confirm that in the absence of endogenous galectin-1 a functional defect in the Foxp3+CD4+Treg cells is involved in the severe response to DSS-colitis observed in Lgals1−/− mice, we adoptively transferred CD25highCD127low/− Foxp3+CD4+Treg cells (WT/TRegs) into colitic Lgals1−/− mice." (PMID 34262567, 2021). "Further, the percentage of Foxp3+ IL-10+ TGF-β+ natural Tregs, Foxp3− IL-10+ TGF-β− induced Tregs, CD127− induced Tregs and CD8+ Tregs was measured at different time points in DSS-induced experimental colitis model in murine lamina propria lymphocytes, mesenteric lymph nodes and peripheral blood." (PMID 34440615, 2021). "We concluded that the reduced weight in the IL-10fl/fl Foxp3-Cre+ mice was not due to colitis." (PMID 33351782, 2021). "Our current study demonstrates that while an increase in Foxp3 may help alleviate colitis, it is not necessary." (PMID 33717186, 2021).